MIR4435-2 (microRNA 4435-2)
Synonyms: hsa-mir-4435-2; mir-4435-2
Gene: MicroRNA gene on chromosome 2 (111,321,013 to 111,321,086, reverse strand). Ensembl gene ENSG00000266139.
Diseases named in the same sentence as MIR4435-2 in open-access papers:
MIR4435-2 is named in the same sentence as 8 diseases in open-access papers, as found by Europe PMC text mining. Sharing a sentence is not in itself a finding about the gene and the disease. The quoted sentences say what the papers report.
gastric cancer (1 paper, 2020). A primary or metastatic malignant neoplasm involving the stomach. "MIR4435-2HG is the host gene of MIR4435-2, which is considered to be a biomarker in various cancers, such as oral squamous cell carcinoma, non-small-cell lung cancer cells, prostate carcinoma, gastric cancer, hepatocellular carcinoma and lung cancer." (PMID 33091878, 2020).
MIR4435-2 also shares sentences with these, for which no sentence is quoted: cancer (1 paper); hepatocellular carcinoma (1); lung carcinoma (1); myocardial infarction (1); non-small cell lung carcinoma (1); oral squamous cell carcinoma (1); prostate carcinoma (1).